MYH11 (myosin heavy chain 11)
Diseases named in the same sentence as MYH11 in open-access papers (continued):
Sharing a sentence is not in itself a finding about the gene and the disease.
aortic aneurysm (continued). "Moreover, pathogenic mutations in several genes have been related to non-syndromic CHD with PDA being a prominent phenotype, including FLNA-related PDA and periventricular heterotopia and MYH11/ACTA2-related PDA and aortic aneurysm." (PMID 36010266, 2022).
acute promyelocytic leukemia (15 papers, 2009 to 2024). An aggressive form of acute myeloid leukemia (AML), characterized by arrest of leukocyte differentiation at the promyelocyte stage, due to a specific chromosomal translocation t(15;17) in myeloid cells. "Assays have been developed for three phenotypes of particular clinical significance: NPM1, Core Bind Factor (CBF)-AML (referring to the fusions gene RUNX1::RUNX1T1 and CBFB::MYH11) and Acute Promyelocytic Leukemia (APL) (referring to the fusion gene PML::RARA)." (PMID 35892893, 2022). "Importantly, PCR assays have been developed for three AML phenotypes: (i) acute promyelocytic leukemia (APL) (fusion gene PML::RARA); (ii) patients with NPM1 and CBF–AML (RUNX1::RUNX1T1 and CBFB::MYH11); and (iii) AML with fusion genes BCR::ABL1, KMT2::MLLT3, and DEK::NUP214." (PMID 37345204, 2023).
aneurysm (15 papers, 2021 to 2025). Bulging or ballooning in an area of an artery secondary to arterial wall weakening. "Genetic factors also play an important role, such as ACTA2 mutations that affect smooth muscle actin and MYH11 mutations that alter smooth muscle contractile proteins, increasing the risk of aneurysms." (PMID 40176978, 2025). "Proteins such as MYH11 and ACTA2, known for their involvement in smooth muscle contraction and structural stability, have been implicated in aneurysm pathogenesis through their influence on vascular smooth muscle cell (VSMC) function." (PMID 40881324, 2025). "Comparing smooth muscle cell markers such as Acta2, Tagln, Myl9, Myl6, Cnn1, and Myh11, these markers were expressed less in thoracic aneurysm SMCs, suggesting a less-differentiated state of the thoracic aneurysm SMCs." (PMID 39590192, 2024). "The otherwise reduced expression level of the marker genes of contractile VSMCs (including Myocd, Srf, Myh11, Cnn1, Cnn2, and Tagln) in aneurysms was rescued in FAM3A-overexpressing aortas." (PMID 37660071, 2023). "MYH11, COL1 (collagen-1), and MGP were detected to show the characteristics of the mural cells in aneurysms." (PMID 35874788, 2022). "Lenvatinib halts aneurysm growth in murine AAA and induces myosin heavy chain 11 expression." (PMID 34185710, 2021).
Aortic dissection (14 papers, 2014 to 2025). Aortic dissection refers to a tear in the intimal layer of the aorta causing a separation between the intima and the medial layers of the aorta. "Yin's study found that MYH11 is a central gene in acute aortic dissection and, according to immune infiltration analysis, MYH11 is associated with macrophages M2." (PMID 40616092, 2025). "The present study takes a comprehensive, data-driven, unbiased approach, combining transcriptomics and metabolomics to further explore the conditions that predispose bearers of Myh11 K1256del to aortic dissection." (PMID 37894894, 2023). "To investigate the pathological mechanisms of aortic dissection associated with Myh11 K1256del, we administered Ang II (1000 ng/kg/min) to WT (n = 16) and Myh11∆K/+ (n = 15) males at eight weeks of age with osmotic pumps." (PMID 35614093, 2022). "A heterozygous missense variant of uncertain significance was detected in MYH11 gene which is increasingly recognized to be belonging to the familial/hereditary thoracic aneurysm and aortic dissection group of disorders." (PMID 35372177, 2022). "This altered property of Myh11 K1256del aortas increases association with the onset of aortic dissection." (PMID 35614093, 2022). "In humans, 10 genes, in addition to Myh11, are also involved in the pathogenesis of acute aortic dissection." (PMID 37894894, 2023). "Downregulation of genes linked to Ehlers–Danlos and Loeys–Dietz syndromes suggests that the pathogenesis of aortic dissection in Myh11 K1256del mice and patients with FTAAD may show similarities to the pathogenesis of Ehlers–Danlos and Loeys–Dietz syndromes." (PMID 40869178, 2025). "Upon angiotensin II stimulation, mice carrying Myh11 K1256del develop aortic dissection." (PMID 40869178, 2025). "However, the expression of these genes in Myh11ΔK/ΔK aortas was not significantly lower than that in wild-type aortas, indicating that a predisposition to aortic dissection in mice harboring the Myh11 K1256 deletion mutation involves a pathway not previously recognized as associated with FTAAD." (PMID 37894894, 2023). "We recently showed that mice lacking K1256 of Myh11 developed aortic dissection when stimulated with angiotensin II, despite the absence of major pathological phenotypic abnormalities prior to stimulation." (PMID 37894894, 2023).
eosinophilia (11 papers, 2014 to 2026). "Some extremely rare fusion genes, such as CSNK2A1::PDGFRB, CBFB::MYH11, and NSD3::NUTM1, have been identified in patients with eosinophilia using RNA−seq techniques." (PMID 38992589, 2024). "However, emerging evidence suggests that a subset of patients estimated at approximately 15% of CBFB::MYH11 AML cases may present without significant eosinophilia, complicating morphological diagnosis." (PMID 41300735, 2025).
gastric cancer (10 papers, 2018 to 2025). A primary or metastatic malignant neoplasm involving the stomach. "The study found that compared with the low microsatellite unstable group, the incidence of MYH11 frameshift mutation was higher in patients with high microsatellite-unstable (MSI) gastric cancer and CRC." (PMID 33747044, 2021). "For example, for MYH11 prostate and stomach cancer have the highest CLIFI values matching the protein expression levels." (PMID 39624167, 2024). "Out of the most significantly down-regulated genes in BM, tumor suppressive implications have been reported for myosin heavy chain 11 (MYH11) in gastric cancer and integrin subunit α 8 (ITGA8)." (PMID 36361816, 2022). "MYH11 expression is downregulated in gastric carcinoma and is indicative of a dismal clinical prognosis." (PMID 35178409, 2021). "Furthermore, we found that assessing the HDS and MYH11+ fibroblasts could increase prognosis-based stratification accuracy in gastric cancer patients." (PMID 37649598, 2023). "Furthermore, in gastric cancer, MYH11 was found to be reduced in GC, whereas MYH11 upregulation has been shown to inhibit tumor growth." (PMID 39762799, 2025). "In gastric cancer, DNMT3B promotes tumor progression by methylating the MYH11 gene, thereby decreasing its expression and allowing the increase of TNFRSF14, which supports cancer development." (PMID 39185313, 2024). "High levels of MYH11+ fibroblasts and CD234+ endothelial cells may be poor prognostic factors for patients with gastric cancer." (PMID 37649598, 2023). "However, the roles of SFRP2+ fibroblasts, MYH11+ fibroblasts, CD234+ endothelial cells and CD69+ fibroblasts are not clear in gastric cancer." (PMID 37649598, 2023).
Hypertension (9 papers, 2012 to 2025). The presence of chronic increased pressure in the systemic arterial system. "We sought to determine if hypertension in combination with a “variant of uncertain significance” that disrupts protein function, MYH11 p.Arg247Cys, would induce aortic dissections in a mouse model." (PMID 40027514, 2025). "Expressed in arteries, MYH11 encodes for smooth muscle myosin heavy chains and has been linked to dominant familial thoracic aortic aneurysm [MIM: 132900], for which hypertension represents a leading risk factor." (PMID 38185688, 2024). "NDE1 and MYH11 were involved in the Rho GTPase effectors pathway whose important role in the pathogenesis of vasospasm, hypertension, pulmonary hypertension, and heart failure had been demonstrated." (PMID 36869404, 2023). "Both MYH11 and fibronectin promote VSMCs plasticity and synthetic phenotype in hypertension pathogenesis." (PMID 35033179, 2022). "The DNAm variation of MYH11 might influence the function of SMC and hence took part in the pathogenesis of hypertension." (PMID 36869404, 2023).
lung carcinoma (7 papers, 2016 to 2025). "ACTG2 can also affect hepatocellular carcinoma cell migration and tumor metastasis, and MYH11 may play a pivotal function in the progression of lung cancer and bladder cancer." (PMID 35768705, 2022). "One subtype (MYH11+ α‐SMA+) present in early‐stage lung cancer promotes T‐cell marginalization through the secretion of collagen IV, while the other subtype (FAP+ α‐SMA+) found in late‐stage lung cancer repels T cells through the secretion of collagen XI/XII, exerting an immunosuppressive effect." (PMID 41164803, 2025).
prostate carcinoma (7 papers, 2008 to 2024). A carcinoma that arises from epithelial cells of the prostate gland. "MYH11 is a member of the Myosin family, which regulates functions, such as signal transduction, muscle contraction, and cell movement in the body, and the mutation of MYH11 has also been observed in prostate cancer, however, further exploration is needed." (PMID 35909899, 2022). "We analyzed breast and prostate cancer samples for those MYH11 regions that harbored somatic mutations in CRCs." (PMID 18796164, 2008). "The sample (LuCaP73) harboring the candidate somatic MYH11 frameshift mutation was a xenograft specimen originating from a hormone-refractory prostate cancer." (PMID 18796164, 2008). "The aim of the current work was to investigate the possible role of somatic MYH11 mutations in two other common cancer types, breast and prostate cancer." (PMID 18796164, 2008). "The aim of this study was to investigate the role of somatic MYH11 mutations in two common tumor types; breast and prostate cancers." (PMID 18796164, 2008). "In prostate cancers, an ATPase activating candidate somatic MYH11 mutation (c.5798delC) was identified in one xenograft sample only." (PMID 18796164, 2008). "Here we have extended the analysis of the role of myosins in tumor development and analyzed sizable sets of breast and prostate cancers for somatic mutations in the key regions of the MYH11 gene (altogether 8 out of 42 coding exons, covering approximately 18% of the coding region)." (PMID 18796164, 2008). "For example, the MYH11 protein has a high magnitude of naCLIFI values for thymoma (<0) and prostate cancer (> 0) in all models, with the boosting models showing greater variability due to these predicting errors of prior trees." (PMID 39624167, 2024). "However, despite MYH11 being the most important protein for prostate cancer prediction and the CLIFI values indicating a bimodal distribution, the UMAP shows only one cluster." (PMID 39624167, 2024). "Little evidence for a role of somatic MYH11 mutations in the formation of breast or prostate cancers was obtained in this study." (PMID 18796164, 2008). "In conclusion, somatic mutations in the regions of MYH11 that are important for colorectal tumor formation are not frequent in breast or prostate cancers." (PMID 18796164, 2008). "This mutation may have occurred by chance and therefore more evidence is needed to establish whether MYH11 has a role in prostate cancer development." (PMID 18796164, 2008). "The resulting CLIFI value distributions indicated heterogeneity in the expression of several proteins (MYH11, ERα, BCL2) across different cancer types (including brain glioma, breast, kidney, thyroid and prostate cancer) aligning with the original raw expression data." (PMID 39624167, 2024). "Differential ERα expression has previously been reported in prostate cancer patients, whereas, to the best of our knowledge, differential MYH11 expression has not;the results shown here would therefore warrant further investigation." (PMID 39624167, 2024).
dissection (6 papers, 2007 to 2023). The separation and isolation of tissues for surgical purposes, or for the analysis or study of their structures. "A mutation in the myosin heavy chain gene (MYH11), indicating a high risk of aortic dissection but a low impact on other vascular systems and organs, was identified." (PMID 38060745, 2023).
familial thoracic aortic aneurysm (6 papers, 2022 to 2025). "The mutation of the Myh11 gene may cause familial thoracic aortic aneurysm and dissection heart, in which the aortic was enlarged near the heart." (PMID 36034815, 2022). "However, MYH11 mutations are known to cause familial thoracic aortic aneurysms." (PMID 35711915, 2022). "MYH11 (OMIM: 160745) encodes the primary contractile protein in smooth muscle cells and is associated with familial thoracic aortic aneurysms and dissections." (PMID 40534548, 2025). "Infants with monoallelic mutations in MYH11 can suffer both familial thoracic aortic aneurysm and PDA70, and MYH11 R712Q mutation causes diminished myosin motor elasticity." (PMID 34350653, 2022).
breast carcinoma (5 papers, 2008 to 2020). "To date, the function of MYH11 in breast cancer remains elusive." (PMID 33216733, 2020). "In this study, no somatic MYH11 mutations were found in breast cancer samples." (PMID 18796164, 2008). "We found that MYH11, TP63 and ELF5 were downregulated in breast cancer tissues, which is consistent with previous findings highlighting TP63 and ELF5 as tumor suppressors." (PMID 33216733, 2020). "Analysis of 155 breast cancer samples for selected MYH11 exons revealed no somatic alterations." (PMID 18796164, 2008).
dementia (5 papers, 2022 to 2024). Loss of intellectual abilities interfering with an individual's social and occupational functions. "In particular, MYH11 overexpressed in Knight-C4 has been reported to be associated with the risk of dementia." (PMID 38687811, 2024). "Non-coding variants in MYH11 have also been found to be associated with dementia in women with differential expression in microarray study of frontal cortex." (PMID 39588545, 2024). "The host gene of CircMYH11 is MYH11, which was confirmed that non-coding variants in MYH11 are associated with dementia in women." (PMID 36506317, 2022). "Interestingly, MYH11 has recently been reported to be differentially expressed in the female AD cortex, and variants within the gene are associated with dementia in females." (PMID 37371093, 2023).
heart failure (5 papers, 2019 to 2025). Inability of the heart to pump blood at an adequate rate to meet tissue metabolic requirements. "Notably, no loci linked to MYH11 have been associated with cardiac hypertrophy or heart failure in GWAS." (PMID 39185210, 2024).
aneurysmal disease (4 papers, 2021 to 2025). "This analysis revealed striking differences in the behavior of each subset, which included opposite direction of change for transcripts derived from genes critically involved in aneurysmal disease such as Myh11, Acta2, Flna, Smtn, and Tagln." (PMID 35463747, 2022). "However, despite causing cardiovascular abnormalities, complete loss of ACTA2 and MYH11 protein expression does not cause aneurysm formation in mice which makes these models unsuitable for studying ACTA2 and MYH11 induced aneurysmal disease development." (PMID 35492343, 2022).
asthma (4 papers, 2015 to 2025). "Studies show that MYH11 expression is increased in bronchial biopsies from patients with asthma, particularly of splice variants whose function increase shortening velocity and associated with greater airway narrowing." (PMID 35578269, 2022). "Among all the MYH11 + COL1A1 + stromal cells, we observed a significant increase in the cell proportion of Myo/SMC and VSMC in AS compared to NC (Fisher’s exact test, FDR < 0.05), suggesting an abnormal increase of myofibroblast and VSMC associated with the pathology of asthma." (PMID 38317239, 2024). "This study confirmed the expression of peptides corresponding to ACTA2, ACTB, ACTG1, MYH11, FLNA, MYL9, and TAGLN in both control guinea pigs and the asthma model." (PMID 40980809, 2025). "Based on immunohistochemistry data, the interactomes related to the expression of MYH11, MYL9, ACTG1, ACTA2, ACTB, TAGLN, and FLNA in the bronchial smooth muscle of guinea pigs in an asthma model were generated." (PMID 40980809, 2025). "MYH11, MYL9, ACTA2, and TAGLN are involved in various pathologies, including the excessive contraction observed in ASM in asthma." (PMID 40980809, 2025). "Among the top genes are ones that have been previously related to asthma (e.g., APOE, CHI3L1, EGR1, MYH11, OXTR, SERPINB2, SOCS3) and corticosteroid-resistant asthma (e.g., FOS) though not necessarily in humans or via changes of the ASM." (PMID 26207385, 2015).
coronary artery disease (4 papers, 2019 to 2025). "Additionally, three genetic risk loci (rs216158, rs9972711, rs12691049) encompassing MYH11 have been linked to coronary artery disease." (PMID 39185210, 2024). "We also performed ELISA to investigate the corresponding proteins levels of selected genes and showed that serum levels of SPP1, CD36, ATP6V0D2, CHI3L1, MYH11, and BDNF were differentially expressed in patients with coronary heart disease compared with healthy subjects." (PMID 31682178, 2019).
hypertrophic cardiomyopathy (4 papers, 2021 to 2025). A condition in which the myocardium is hypertrophied without an obvious cause. "We have also identified a MYH11 rare variant of unknown significance (VUS), MYH11 p.Arg247Cys, in patients with thoracic aortic disease, and disruption of the corresponding amino acid in MYH7 causes familial hypertrophic cardiomyopathy." (PMID 40027514, 2025). "Notably, tropomyosin 1 (TPM1), myosin light chain 2 (MYL2), myosin heavy chain 11 (MYH11) and other DEPs were involved in hypertrophic cardiomyopathy, dilated cardiomyopathy and other pathways." (PMID 33785854, 2021).
Marfan syndrome (4 papers, 2014 to 2025). A disorder of the connective tissue. "Among them, 51 patients had genetically confirmed HTAD (Marfan syndrome (FBN1), Loeys-Dietz syndrome (TGFBR1, TGFBR2, SMAD3, TGFB2), vascular Ehlers-Danlos syndrome (COLSA1), and non-syndromic HTAD (ACTA2, MYH11, MYLK))." (PMID 41310758, 2025).
Megacystis (4 papers, 2019 to 2026). Dilatation of the bladder postnatally. "Megacystis-Microcolon-Intestinal Hypoperistalsis Syndrome has five types caused by MYLK, MYH11, LMOD1, MYL9, and ACTG2 genes and has unknown prevalence." (PMID 39480826, 2024). "Genetic testing was performed to rule out megacystis-microcolon syndrome, but specific ACTG2 and MYH11 mutations were not tested due to the limited availability of comprehensive genetic panels, which we recommend for future cases to better characterize the underlying pathophysiology." (PMID 41149692, 2025).
sarcoma (4 papers, 2020 to 2023). A usually aggressive malignant neoplasm of the soft tissue or bone. "Notably, human MYH11 protein, which is normally not expressed in RMS, is a marker of sarcoma pleomorphism, and an effector of lysosomal exocytosis downstream of Neu1 downregulation." (PMID 36127469, 2022).
Stroke (4 papers, 2021 to 2025). Sudden impairment of blood flow to a part of the brain due to occlusion or rupture of an artery to the brain. "MYH11 has been extensively studied for its potential involvement in vascular disease and stroke which are associated with AD." (PMID 37705610, 2023). "This case report highlights the risk for vascular abnormalities, including cerebrovascular disease, in MYH11 pathogenic variants and underscores the importance of vigilant monitoring and early prophylactic interventions for stroke prevention in this patient population." (PMID 41040781, 2025). "We report a case of a rare heterozygous MYH11:c.3818G>T, p.(Arg1273Leu) missense variant in a patient with multiple brain infarcts early in life, multiple intracranial arterial aneurysms and stenotic lesions, aortic aneurysmal formation, and a familial history of stroke." (PMID 41040781, 2025).